IGKV6D-41 (immunoglobulin kappa variable 6D-41 (non-functional))
Description:
Probable non-functional open reading frame (ORF) of V region of the variable domain of immunoglobulin light chains. Non-functional ORF generally cannot participate in the synthesis of a productive immunoglobulin chain due to altered V- (D)-J or switch recombination and/or splicing site (at mRNA level) and/or conserved amino acid change (protein level). Immunoglobulins, also known as antibodies, are membrane-bound or secreted glycoproteins produced by B lymphocytes. In the recognition phase of humoral immunity, the membrane-bound immunoglobulins serve as receptors which, upon binding of a specific antigen, trigger the clonal expansion and differentiation of B lymphocytes into immunoglobulins-secreting plasma cells. Secreted immunoglobulins mediate the effector phase of humoral immunity, which results in the elimination of bound antigens. The antigen binding site is formed by the variable domain of one heavy chain, together with that of its associated light chain. Thus, each immunoglobulin has two antigen binding sites with remarkable affinity for a particular antigen. The variable domains are assembled by a process called V-(D)-J rearrangement and can then be subjected to somatic hypermutations which, after exposure to antigen and selection, allow affinity maturation for a particular antigen.
Synonyms: A14
Gene: Immunoglobulin variable (V) gene on chromosome 2 (90,069,662 to 90,070,238, forward strand). Ensembl gene ENSG00000211626.
Subcellular location: Secreted; Cell membrane
Gene Ontology:
Biological process: immune response
Cellular component: extracellular region; immunoglobulin complex; plasma membrane
Homologues: Orthologues: macaque IGKV6D-41 (79% identical), mouse Igkv5-39 (65% identical), mouse Igkv5-45 (65% identical), mouse Igkv5-48 (65% identical), mouse Igkv5-43 (64% identical), rat Igkv5-45l1 (62% identical), mouse Igkv5-37 (59% identical). Paralogues in human: IGKV6D-21 (76% identical), IGKV6-21 (75% identical), IGKV1-12 (67% identical), IGKV1-27 (67% identical), IGKV1-33 (67% identical), IGKV1-9 (67% identical), IGKV1D-12 (67% identical), IGKV1D-33 (67% identical), IGKV1-17 (65% identical), IGKV1-39 (65% identical), IGKV1-6 (65% identical), IGKV1D-13 (65% identical), and 81 more.